SREBF2 (sterol regulatory element binding transcription factor 2)
Diseases named in the same sentence as SREBF2 in open-access papers (continued):
Sharing a sentence is not in itself a finding about the gene and the disease.
cataract (1 paper, 2023). Partial or complete opacity of the crystalline lens of one or both eyes that decreases visual acuity and eventually results in blindness. "Mutations in Srebf2 may therefore also cause cataracts in ICR." (PMID 37875594, 2023).
Cirrhosis (1 paper, 2024). A chronic disorder of the liver in which liver tissue becomes scarred and is partially replaced by regenerative nodules and fibrotic tissue resulting in loss of liver function. "The investigators discovered that elevated levels of lipopolysaccharide (LPS) in patients with cirrhosis resulted in dysregulation of SREBF2 expression." (PMID 38840241, 2024).
coronary stenosis (1 paper, 2019). Narrowing of the coronary artery lumen diameter. "SREBF2 was overexpressed in patients with coronary stenosis ≥50% vs subjects with stenosis <50% (p = 0.036)." (PMID 30673762, 2019).
coronary thrombosis (1 paper, 2008). Coagulation of blood in any of the coronary vessels. "The combination of the SREBF-2 C allele and the SCAP G allele was present in 8 of the 20 men (40%) with coronary thrombosis, whereas the SREBF-2 C allele in combination with the SCAP AA genotype was present in 2 of the 20 men (10%) with coronary thrombosis." (PMID 19116028, 2008).
frontotemporal dementia (1 paper, 2022). Frontotemporal dementia (FTD) comprises a group of neurodegenerative disorders, characterized by progressive changes in behavior, executive dysfunction and language impairment, as a result of degeneration of the medial prefrontal and frontoinsular cortices. "Interestingly, CREB and SREBF2 have been documented to interact with TDP3, a major constituent of neuronal inclusions in ALS and frontotemporal dementia." (PMID 35370543, 2022).
Granuloma (1 paper, 2024). A compact, organized collection of mature mononuclear phagocytes, which may be but is not necessarily accompanied by accessory features such as necrosis. "Additionally, spatial transcriptomics and scRNA-seq data of human sarcoidosis lesional and non-lesional skin revealed increased SREBF1 and SREBF2 expression in sarcoidosis granulomas." (PMID 38353578, 2024).
hepatitis B (1 paper, 2025). "GSE83148 contained 6 healthy and 122 HBV‐infected liver tissue samples, the results of which showed that SREBF2 expression was significantly higher in hepatitis B tissues than in normal liver tissues." (PMID 40476478, 2025). "The expression of SREBF2 in hepatitis B‐related liver cancerous tissues was further higher than that in non‐hepatitis B‐related cancerous tissues." (PMID 40476478, 2025).
kidney cancer (1 paper, 2024). Primary or metastatic malignant neoplasm involving the kidney. "Additionally, DUSP18 and SREBF2 mRNA levels were significantly positively correlated in TCGA-COAD, and pan-cancer analyses revealed a similar correlation in most tumors, including CRCs, liver and kidney cancers." (PMID 38992029, 2024).
knee osteoarthritis (1 paper, 2021). "The present data suggest that STM attenuated chondrocyte injury induced by IL-1β by regulating ferroptosis via down-regulation of SREBF2, and may have potential as a novel therapeutic method for knee osteoarthritis." (PMID 34806937, 2021).
lymphoma (1 paper, 2020). A malignant (clonal) proliferation of B- lymphocytes or T- lymphocytes which involves the lymph nodes, bone marrow and/or extranodal sites. "Furthermore, lymphoma cells from Lck-Dlx5;Lck-MyrAkt2 mice had elevated expression of genes encoding components of the Srebf2 pathway, and their expression was suppressed when β-catenin/Tcf inhibitors were used." (PMID 32985581, 2020). "These lymphoma cells had high Lef1 levels and were highly sensitive to β-catenin and Srebf2-cholesterol synthesis inhibitors." (PMID 32985581, 2020). "Combined RNA-seq and ChIP-seq analysis of lymphomas from Lck-Dlx5;Lck-MyrAkt mice demonstrated that β-catenin directly regulates genes involved in sterol regulatory element binding transcription factor 2 (Srebf2)-cholesterol synthesis." (PMID 32985581, 2020). "Lymphoma cells from Lck-Dlx5;Lck-MyrAkt2 mice were treated with PFK118-310 at 1 μM for 20 h and then subjected to whole transcriptome analysis, which revealed altered expression of genes encoding Srebf2-cholesterol synthesis pathway members and cell cycle regulators." (PMID 32985581, 2020).
malnutrition (1 paper, 2025). Inadequate nutrition resulting from poor diet, malabsorption, or abnormal nutrient distribution. "As an indication of malnutrition and resultant wasting syndrome, elevated asparagine synthetase (Asns) and reduced insulin growth factor 1 (Igf1) expression in livers from LEC Srebf2–/– mice were found, which resemble Plagl2-knockout mice in which lacteals in jejunum are also dilated." (PMID 41122969, 2025).
myeloproliferative neoplasm (1 paper, 2020). A clonal hematopoietic stem cell disorder, characterized by proliferation in the bone marrow of one or more of the myeloid (i.e., granulocytic, erythroid, megakaryocytic, and mast cell) lineages. "Given that MAPK1 has been shown to be a miR-28-5p target in myeloproliferative neoplasm, it is possible that miR-28-5p regulates SREBF2 both directly and indirectly through MAPK." (PMID 32028704, 2020).
ovarian tumors (1 paper, 2024). "Furthermore, immunohistochemistry staining (IHC) and real-time quantitative PCR (RT-qPCR) were employed for the validation of the expression and biological functions of core proteins, including HSPAA1, HSPA8, SOD1, and transcription factors SREBF2 and GTAT2, in ovarian tumors." (PMID 38166541, 2024). "RT-qPCR results showed that SOD1 exhibited consistent expression with HSP90AA1 and HSPA8, while SREBF2 and GTAT2 were highly expressed in non-malignant ovarian tumor tissues and significantly decreased in high-grade serous ovarian cancer samples." (PMID 38166541, 2024).
polycystic ovary syndrome (1 paper, 2025). A disorder that manifests as multiple cysts on the ovaries. "A study suggested that PER1 promotes ferroptosis and dysfunctional lipid metabolism in granulosa cells in polycystic ovary syndrome (PCOS) by inhibiting sterol regulatory element-binding factor 2 (SREBF2)/arachidonate 15-lipoxygenase (ALOX15) signaling pathway." (PMID 41451215, 2025).
prediabetes (1 paper, 2019). "H3K4me3 was enriched at the promoter of E2F1, LPL, SREBF2, SCD1, PPARG and IL6 in lean normoglycemic compared to morbid obese subjects with prediabetes." (PMID 30958852, 2019).
psychotic disorder (1 paper, 2021). An abnormal condition of the mind that involves a loss of contact with reality. "A total of 113 patients with psychotic disorders were genotyped for the SREBF2 gene and the INSIG2 polymorphisms." (PMID 34683084, 2021).
renal agenesis (1 paper, 2019). Renal agenesis (RA) is a form of renal tract malformation characterized by the complete absence of development of one or both kidneys (unilateral RA or bilateral RA respectively), accompanied by absent ureter(s). "Other interesting candidate adaptive genes include HLA-DMA involved in immunity, FRAS1 associated with renal agenesis, SREBF2 related to female reproduction and DISC1 associated with response to the ultraviolet (UV) exposure." (PMID 34691999, 2019).
sarcopenia (1 paper, 2026). Progressive decline in muscle mass due to aging which results in decreased functional capacity of muscles. "Our correlation bubble map indicated that numerous immune cells within sarcopenia samples characterised by low FAMs were strongly correlated, with SREBF2 being most significantly and inversely related to T helper cells (R = −0.746, P < 0.05)." (PMID 41460756, 2026). "FABP3, PPARGC1A, and SREBF2 received the highest relevance scores, indicating that these genes may serve as more prominent mediators linking sarcopenia with fatty acid metabolism." (PMID 41460756, 2026). "In contrast, sarcopenia group showed remarkably reduced PCTP (P < 0.001), SREBF2 (P < 0.001), and PPARGC1A (P < 0.05) levels." (PMID 41460756, 2026). "The qPCR results demonstrated that FABP3 (P < 0.001), PECR (P < 0.01), and OPN3 (P < 0.001) expression markedly increased in D‐gal‐induced sarcopenia compared with control groups, whereas PCTP (P < 0.001), SREBF2 (P < 0.001), and PPARGC1A (P < 0.05) levels dramatically decreased." (PMID 41460756, 2026).
thymic lymphomas (1 paper, 2015).
tumor (122 papers, 2013 to 2026). "Furthermore, we found that deletion of Srebf2 from LSCC tumours was associated with reduced nuclear expression of ΔNP63." (PMID 37202505, 2023). "In WT tumor cells, regulons associated with NFKB1, XBP1, JUN, SREBF2, and EHF exhibited elevated activity." (PMID 40767963, 2025). "As a master regulator of cholesterol biosynthesis, SREBF2 depletion decreases essential membrane components and signaling lipids, repressing tumor proliferation in nutrient-scarce microenvironments." (PMID 41283357, 2025). "Taken together, our observations have revealed a crucial role for DUSP18/USF1/SREBF2-lanosterol signaling in tumor immunosuppressive reprogramming." (PMID 38992029, 2024). "In turn, USF1 induces the SREBF2 gene, which allows cells to accumulate the cholesterol biosynthesis intermediate lanosterol and release it into the tumor microenvironment (TME)." (PMID 38992029, 2024). "We observed that SREBF2 KD in the DAXX OE cells significantly attenuated the levels of lipogenic enzymes and tumor growth, implying that SREBP2 is a critical effector of DAXX’s oncogenic function." (PMID 37045819, 2023). "Critically, CRISPR/Cas9-mediated deletion of Srebf2 from KPL tumours (KPLS2) resulted in a marked reduction in tumour load and reduced expression of the SCC marker ΔNp63." (PMID 37202505, 2023). "We, therefore, used the same AAV-based CRISPR/Cas9 strategy to target Srebf1 or Srebf2 in KPL tumours (KPLS1 and KPLS2)." (PMID 37202505, 2023). "Both PMVK and SREBF2 expression were elevated in tumour tissues (n = 1093) compared with adjacent normal tissues (n = 104), whereas miR-874 expression was decreased in tumour tissues compared with corresponding normal tissues." (PMID 36323841, 2022). "SREBF2 expression was higher in BC metastatic tumour tissues of brain metastases (BC‐BM) compared to other metastases (BC‐OM)." (PMID 35678121, 2022). "Observation from tumor tissues of mice showed that the tumor tissues of mice with low SREBF2 expression were significantly reduced, while those mice with further overexpression of PRSS8 showed an increased tendency." (PMID 34823420, 2021). "For example, cholesterol was found to promote intestinal stem cell growth and tumorigenesis in intestinal-specific Srebf2 transgenic mice; and biosynthesis of cholesterol played a determinant role for tumor formation in Apcmin/+ mice model." (PMID 34621019, 2021). "We validated miR-28-5p/SREBF2 interaction, demonstrating that SREBF2 inhibition affects almost all the tumor processes altered by miR-28-5p re-expression, suggesting that SREBF2 is an important mediator of miR-28-5p TS activity." (PMID 32028704, 2020). "We demonstrated that SREBF2 is one of the mediators of the miR-28-5p TS activity, given that its inhibition determined a decrease of tumor cell survival and proliferation and to a lesser extent invasion and migration." (PMID 32028704, 2020). "Only a small subset of mucinous breast carcinomas tumours was observed to have high expression of SREBF2 (p = 0.002, fold change = 1,229)." (PMID 32577155, 2020). "Having shown that miR-33a is decreased in PCa and acts as a tumor suppressor, we examined the levels of SREBF2 in PCa compared to benign prostate tissue." (PMID 28947967, 2017). "Here, we found SREBF1 and SREBF2 genes also exhibited increased expressions in tumor tissues." (PMID 37164975, 2023). "Moreover, cholesterol synthesizing enzyme genes HMGCS1 and HMGCR, as well as SREBF2 genes that regulate genes in cholesterol synthesis pathway, all were elevated in tumor and interfacing lymphoid tissues." (PMID 37164975, 2023). "In addition, a significant positive correlation between the levels of SREBF1 and SREBF2 was also evident in the tumor samples (P=0.0011)." (PMID 36300096, 2022).
tumor (continued). "In accordance with these observations we demonstrated that the inhibition of SREBF2 in DU-145 cells induced an anti-tumor activity also in this case by affecting various tumor characteristics such as cell proliferation, survival and to a lesser extent, invasion and migration." (PMID 32028704, 2020). "By co-activating metabolic deprivation (via SREBF2 inhibition), loss of invasive potential (via TGF-β suppression), and stress/CTL-induced apoptosis (via HSPA1/CDKN1A), these agents generate a lethal epigenetic storm that suppresses tumor growth, metastasis, and therapy resistance." (PMID 41283357, 2025). "In contrast, six genes known to inhibit cell proliferation and tumor growth were overexpressed in d-HGP: SIRT6, MPC2, MIR4458HG, ST20-AS1, SREBF2, MRPL40." (PMID 38548918, 2024). "Along with high levels of methylation of PRMT4, PRMT5, PRMT7, and hnRNPA1 in tumor samples, changes in gene alternative splicing were observed, such as those for PPARA, SREBF2, RAB27B, and WDPCP in BRCA, CRC, and PC samples." (PMID 33782401, 2021). "Both TGFβ1 and GDF15 belongs to TGF-β superfamily, TGFβ1 was reported to activate SREBP2 in kidney mesangial cells, SREBF2 activation was dependent on SCAP, SCAP or SREBPs promoted tumor progression in various cancer." (PMID 33123476, 2020). "miRNAs modulate the expression of numerous metabolic factors and enzymes, such as SREBF2, AKT2, G6PD, CPS1, FADS1, and ETNK1, which alter tumor cell responses to chemotherapeutic treatments." (PMID 27861141, 2016). "Collectively, these results demonstrate that both SREBF1 and SREBF2 support PDAC cell and tumor growth, suggesting that SCAP may be a better therapeutic target than either SREBP1 or SREBP2 alone." (PMID 39240063, 2024). "While deletion of Srebf1 did not alter tumour load, deletion of Srebf2 resulted in a significant reduction in tumour burden in age matched KPLS2 compared to KPL mice." (PMID 37202505, 2023). "Western blot was used to detect the expressions of SREBF2, PRSS8 and SCNN1A in tumor tissues." (PMID 34823420, 2021).
cancer (95 papers, 2012 to 2026). A tumor composed of atypical neoplastic, often pleomorphic cells that invade other tissues. "The lowest mean/median dependency scores for SREBF1 and SREBF2 in any cancer cell type were −0.5 (pancreas) and −0.2 (prostate), respectively." (PMID 39240063, 2024). "The results of pan-cancer analysis in this study describe the expression levels of four genes (Irs2, Plin2, Pnpla2 and Srebf2) in various types of cancerous tissues compared to normal tissues." (PMID 37047411, 2023). "TMEM97, which is transcriptionally controlled by SREBF2, is an intracellular orphan receptor that binds numerous drugs and highly expressed in various proliferating cancer cells involving cell survival, morphology, and differentiation." (PMID 34349727, 2021). "To examine the requirement of the SREBP pathway for cancer cell growth on a wider scale, we examined the Chronos dependency scores for SCAP, SREBF1, and SREBF2 using the Cancer Dependency Map database, which contains genome-wide CRISPR loss-of-function screen data for hundreds of cancer cell lines." (PMID 39240063, 2024). "Thus, chemoresistance and cancer cell survival under high ROS burden obligates high GPx4 and SR‐B1 expression through SREBF2." (PMID 38263873, 2024). "In addition, the increased expression of MSMO1, HMGCS1, MVD, and SREBF2 across solid tumors vs. normal tissues based on the analysis of TCGA datasets further signifies the crucial role of these metabolic genes in multiple cancers." (PMID 37745085, 2023). "Parallel suppression of SREBF2, mediated by decreased H3K27ac through EP300/CBP downregulation, undermines cancer cell metabolic plasticity." (PMID 41283357, 2025). "In other instances, metabolic reprograming involves the synergistic interaction of SREBF2 with other transcription factors such as early growth response element 1 (EGR1) and the nuclear receptor RAR-related receptor gamma (RORγ) to promote cholesterol biosynthesis, particularly in cancer." (PMID 37745085, 2023).
infection (34 papers, 2009 to 2026). The state of being infected such as from the introduction of a foreign agent such as serum, vaccine, antigenic substance or organism. "Last, attending to the expression of regulators of cholesterol homeostasis (bottom), we observed a clear decrease in Nr1h3 and Srebf2 mRNA levels in response to infection, consistent with a scenario where cholesterol uptake and availability are high." (PMID 36453897, 2022). "Comparison of these results with the haploid cell screen revealed that SREBF2 was the only gene in common, making this a strong candidate since it influenced infection in two different screens." (PMID 24516383, 2014). "As total and LDL cholesterol were elevated in the P. gingivalis-infected mice, Srebf2 is likely to be induced by this infection." (PMID 22992388, 2012). "Further studies are required to elucidate how infection regulates Srebf2 expression and subsequently influences lipid metabolism." (PMID 22992388, 2012). "The results obtained from the siRNA and haploid cell screens indicated that components of the sterol regulatory pathway (SREBF2, SCAP, S1P, and S2P) were required for rVSV-ANDV infection." (PMID 24516383, 2014). "A recent parallel genome-wide CRISPR screen also identified SREBF2, but not SREBF1, as a key host factor in SARS-CoV-2 and HCoV-OC43 infection of Cas9-expressing Huh7.5 hepatoma cells." (PMID 36097162, 2022).
cardiovascular disease (6 papers, 2018 to 2025). "Even more interesting is our observation that inhibition of RORγ in combination with ATV, an agent that is widely used and overall well-tolerated in the context of cardiovascular diseases, significantly reduced SREBF2 gene expression." (PMID 38030791, 2024).
blood cancer (1 paper, 2024). "SREBF2 gene expression was increased in patients with different blood cancer types compared to healthy individuals." (PMID 38030791, 2024).
SREBF2 also shares sentences with these, for which no sentence is quoted: steatosis (17 papers); pancreatic cancer (12); colon cancer (10); metabolic disorders (9); colorectal cancer (7); hypothyroidism (7); endothelial dysfunction (6); non-alcoholic fatty liver disease (6); gallstones (5); Type 2 diabetes (5); bladder cancer (4); cholestasis (4); gastric cancer (4); Huntington disease (4); Hyperglycemia (4); osteosarcoma (4); asthma (3); colitis (3); coronary artery disease (3); HCMV infection (3); liver fibrosis (3); lung adenocarcinoma (3); lung squamous cell carcinoma (3); neurodegenerative disease (3); non-small cell lung carcinoma (3); pulmonary fibrosis (3); renal cell carcinoma (3); vitamin D deficiency (3); arteriosclerosis (2); B cell lymphoma (2).
A further 110 diseases each share a sentence with SREBF2 in 2 papers or fewer.